INS (insulin)
Diseases named in the same sentence as INS in open-access papers (continued):
Sharing a sentence is not in itself a finding about the gene and the disease.
Obesity (continued). "Indeed, a low-GI diet is considered the most effective diet for the prevention of obesity by lowering postprandial blood glucose and insulin levels, increase satiety, and decrease energy intake." (PMID 37582773, 2023). "Randomized controlled trials (RCT) demonstrate improvements in insulin sensitivity in youth with obesity regardless of weight loss." (PMID 38108040, 2023). "This may be related to the different method and animal they used for model induction, as they built an obesity rat model of episodic HDF for insulin leptin resistance and lipid perception deficits." (PMID 37893758, 2023). "The balance between the lipogenic effect of cortisol and insulin, which are hormones effective on body fat distribution, and the lipolytic effect of sex steroids and growth hormones can be disrupted, especially in children with obesity." (PMID 36765298, 2023). "miR-802-5p knockdown prevented the development of obesity-mediated IR; moreover, miR-802-5p may target the NeuroD1 and frizzled (Fzd) 5 genes involved in insulin regulatory processes." (PMID 37537674, 2023). "On the other hand, intra-abdominal obesity increases visfatin synthesis, which may enhance obesity while maintaining insulin sensitivity in the peripheral organs." (PMID 38136166, 2023). "Furthermore, youth with comorbid T1D and obesity are developing insulin resistance to their exogeneous insulin." (PMID 37614408, 2023). "Notwithstanding the importance of β-cell oxidative stress in the adaptive changes of β-cell mass and function in obesity, it remains unknown whether maternal oxidative stress impacts β-cell compensation for maternal insulin resistance in pregnancy." (PMID 38229396, 2023). "Therefore, it is significant to discover the differences of insulin secretion and sensitivity in Chinese with different types of obesity." (PMID 36909323, 2023). "According to the “carbohydrate-insulin model” of obesity, an increased proportion of rapidly digestible carbohydrates (i.e., a high glycemic load) in the diet elevates insulin secretion, thus suppressing the release of fatty acids into circulation and directing circulating fat toward storage." (PMID 37703994, 2023). "The influence of obesity on insulin secretion is controversial." (PMID 36909323, 2023). "Interestingly, subgroup analysis showed that the association between hyperandrogenism and NAFLD was prominent in the overweight and/or obesity group and the more insulin-resistant group." (PMID 37591864, 2023). "Interestingly, the obesity-related factors insulin and leptin have been reported to induce an increase in the expression of PLK1." (PMID 37447165, 2023). "Specifically, a high level of IL-1β impairs insulin signalling in the macrophages and peripheral tissues, which will in turn contribute to obesity development, as a slight elevation of insulin in the circulation can effectively inhibit lipolysis and enhance lipogenesis in the adipocytes." (PMID 37627544, 2023). "Moreover, increased epicardial fat thickness has been found to be related to obesity, body mass index, the metabolic syndrome, and heart disease, which are characterized by inflammation, hypertension, and disturbances in insulin sensitivity." (PMID 37663296, 2023). "Although NCDs’ co-occurrence has been previously shown, studies frequently analyzed the association of two conditions only, such as caries and periodontitis; obesity and caries; obesity and periodontitis; obesity and insulin resistance; and insulin resistance and periodontitis." (PMID 37630703, 2023). "Obesity can cause pancreatic insufficiency and reduce insulin secretion as fat cells are not sensitive to insulin, resulting in hyperglycemia." (PMID 36662790, 2023). "Overall, this suggests that the GLP-1 pathway overlaps with the insulin pathway, and it could compensate for the DM, obesity, or AD damage to the insulin pathway." (PMID 37623897, 2023).
Obesity (continued). "Similar to our findings, one other study supported a significant inverse association between MCP-1 and insulin sensitivity among adolescents with obesity while two studies failed to support this association." (PMID 37299403, 2023). "Thus, boosting brown fat activity leads to reduced adiposity, improved insulin action and glucose handling, contributing to protection against obesity and metabolic dysfunction." (PMID 38010450, 2023). "A decrease in body weight by treatment with anti-obesity substances could beneficially affect sensitivity to insulin and tolerance to glucose, and it might positively affect lipid metabolism in the liver." (PMID 36678151, 2023). "Additionally, risk factors for the development of laminitis were proposed to include the presence of endocrine disease and insulin dysregulation, obesity, high energy feeding regimes, access to pasture and sparse exercise regimens." (PMID 37328910, 2023). "In addition, a reduction in mean HbA1c values, reduced insulin requirements and improved insulin sensitivity were also observed, probably also due to the beneficial effect on overweight and obesity." (PMID 37630698, 2023). "Furthermore, TNF-a in obesity disrupts endothelial integrity by inducing endotheliocyte apoptosis, which is prevented by insulin." (PMID 36674022, 2023). "Previously, we had shown that bile acids and FGF19 both affected glucose metabolism by improving insulin sensitivity and glucose-stimulated insulin secretion (GSIS) in lean mice on normal chow, DIO (diet-induced obesity) mice, and obese leptin-deficient (ob/ob) mice." (PMID 36787185, 2023). "Moreover, inhibiting SOCS3 production in adipose tissue of female mice can ameliorate whole-body insulin sensitivity in obesity." (PMID 36609306, 2023). "Clinically, women with gestational diabetes and obesity are on metformin treatment and if the drug is inefficient, these patients unknowingly having a B12 deficiency are given insulin, suggesting the patients are not responsive." (PMID 38140305, 2023). "Otherwise, many confounding factors related to obesity, such as high levels of blood glucose, insulin, amino acids, and growth factors, may influence the MTORC1 pathway (especially RagC/D GTPases)." (PMID 36649084, 2023). "According to recent research, V may have a protective role against obesity and metabolic disorders, partly through inhibiting phosphatases and affecting kinases that are essential for the insulin pathway." (PMID 38075040, 2023). "Additionally, insulin, as the key hormone in obesity, apparently induces different effects at different times during the day." (PMID 36984860, 2023). "Targeting skeletal muscle lipid turnover and the balance between lipolysis, FA uptake, and mitochondrial function/fat oxidation may be an attractive strategy with which to improve insulin sensitivity in obesity and T2D." (PMID 38068801, 2023). "Furthermore, NLRP3 inflammasome suppression has been found to reduce obesity-related inflammation and enhance insulin sensitivity." (PMID 37446154, 2023). "Key hormones, such as insulin, leptin, ghrelin, and cortisol, as well as orexins, hypocretins, and melatonin, are believed to play a crucial role in the complex relationship between sleep and obesity." (PMID 38004130, 2023). "By reducing TNF-α expression, CGWE may improve insulin sensitivity and reduce lipolysis, contributing to its anti-obesity effects." (PMID 37571229, 2023). "Therefore, obesity must be only one factor of a more complex multifactorial process involving the metabolism of leptin, growth hormone, insulin, hypertension, and with Homeostatic Model Assessment (HOMA), triglycerides and VLDL as additional elements." (PMID 37238326, 2023). "Therefore, we herein employed the leptin-deficient obese (Lepob/ob) mouse model and assessed the effects of obesity on Rac1-mediated insulin signaling in skeletal muscle." (PMID 37511290, 2023).
Obesity (continued). "Moreover, miR-26b is downregulated by leptin and this miRNA was found to be reduced in visceral adipose tissue (VAT) in insulin-resistant adipocytes, obese rodent models, and human obesity." (PMID 36674935, 2023). "Thus, insulin is an essential neurohormone in the pathogenesis of obesity, and therefore, reports on the effects of polyphenols on insulin underscore their potential role in obesity." (PMID 36829976, 2023). "Indeed, JNK activation in macrophages is an important driver of metabolic inflammation and impaired insulin signaling in obesity." (PMID 37781916, 2023). "However, under obesity or diabetes, this balance is broken, generating insulin resistance in adipocytes." (PMID 37026009, 2023). "Note that all the SNPs had a reported role in insulin secretion, insulin sensitivity, or obesity." (PMID 36875493, 2023). "Regardless of adiposity levels, most patients with PCOS have high serum insulin and IR obesity." (PMID 36695999, 2023). "Consequently, the AL ratio has been suggested to be a marker of low-grade chronic inflammation in populations with impaired insulin functions and obesity." (PMID 36790383, 2023). "The serum albumin levels and metabolic phenotypes including fasting blood glucose, glucose tolerance tests, and glucose-stimulated insulin secretion were studied in db/db mice or diet-induced obesity mice treated with saline or young, undamaged, and ultrapure rMSA." (PMID 36747238, 2023). "Importantly, both systemic and ICV administration of SHLP2 in mice provided protection against diet-induced obesity, resulting in reductions in body weight and fat mass, as well as improvements in insulin sensitivity." (PMID 37468558, 2023). "Numerous studies have indicated that miRNAs regulate insulin sensitivity, and this effect may be utilized in the treatment of obesity and T2DM." (PMID 36769291, 2023). "Insulin sensitivity affected the cholesterol metabolism to a greater extent than obesity." (PMID 37513825, 2023). "Besides these, there are other hormones like insulin, ghrelin, obestatin, and so on which directly or indirectly affect body weight showing a deep connection between endocrinology and obesity." (PMID 37861729, 2023). "T2DM is predominantly associated with cardiovascular complications, while in patients with T2DM, the prevalence of MAFLD, severe fibrosis, and cirrhosis have been estimated to be 65%, 14%, and 6%, respectively, with obesity and insulin administration being predictors of fibrosis." (PMID 37834153, 2023). "Indeed, the hormone insulin and its structural relation, insulin-like growth factor 1 (IGF-1), have been linked to both carcinogenesis and obesity." (PMID 36038791, 2022). "In addition, some studies have found a correlation between blood EVs concentrations and their miRNA and protein content with obesity and IR; briefly, to understand the molecular mechanism of insulin signaling, further information is provided below." (PMID 35681526, 2022). "Furthermore, we expected sex-dependent effects on FCR in response to central insulin with increased activity in reward-related areas in women with overweight and obesity." (PMID 35715625, 2022). "Indeed, mutant POMCCremiR-29aCKO females exhibited hyperphagic obesity accompanied by fat tissue hypertrophy and insulin resistance (, 4) indicating that miR-29a is critical for normal metabolic balance and is independent of age." (PMID 35490865, 2022). "Given these links between insulin, immune function and cancer, including the exhaustive evidence provided for the connections between obesity, inflammation, insulin-dependent diabetes, and cancer, this serves the logical thinking that there are links between cancer immunology and insulin." (PMID 35244142, 2022). "People living with obesity show reduced insulin transport into the cerebrospinal fluid, resulting in decreased concentrations of centrally available insulin and subsequent reductions in central insulin signalling." (PMID 35860945, 2022).
Obesity (continued). "Decreased insulin sensitivity is a well-known complication of obesity." (PMID 36112590, 2022). "It is important to mention that night sleep duration is correlated with insulin level and obesity by hip/waist and that may add to the burden of metabolic derangement if the subject goes for afternoon napping." (PMID 36299550, 2022). "Furthermore, the long-term HF diet also led to metabolic disorders such as increases in circulating insulin and leptin levels, indicative of insulin and leptin resistance, as classically reported in animal models of diet-induced obesity." (PMID 35498414, 2022). "Although a larger prospective study is warranted to confirm the relationship, surveillance of the development of GO in patients with GD should be considered, particularly for those with obesity-related factors, such as higher fasting plasma insulin and HOMA-IR." (PMID 36556950, 2022). "Additionally, a partial reduction in plasma leptin levels can restore hypothalamic leptin sensitivity and effectively decrease weight gain as well as improve insulin sensitivity in obesity." (PMID 35355566, 2022). "In addition, ABA improves insulin sensitivity and obesity‐related inflammation through a mechanism requiring immune cell PPARγ." (PMID 36355391, 2022). "Several lipid parameters, parameters of insulin–glucose metabolism, liver enzymes, adipokines, and markers of inflammation and early atherogenesis were studied for sex differences across increasing obesity severity grades." (PMID 35246259, 2022). "More importantly, the LI protocol improved insulin sensitivity, reduced fasting insulinemia, improve the level of the obesity-related adiponectin, decreased the level of the pro-inflammatory marker TNF-alpha and Il-6, and positively modulated the levels of exercise-induced myokines, irisin and BDNF." (PMID 35120179, 2022). "Insulin-resistant states related to obesity might be associated with diminished GIP sensitivity, and GIPR expression in human adipose tissue might determine systemic insulin sensitivity." (PMID 35721732, 2022). "It has been reported that differential DNA methylation could explain the link between obesity and insulin metabolism." (PMID 36439251, 2022). "Therefore, we propose that microglial insulin signaling plays a key protective role during the progression of obesity in female mice." (PMID 35328354, 2022). "Possible reasons include that short sleep duration would lead to changes in body hormone levels (leptin, insulin, ghrelin, cortisol) related to obesity and metabolism, accompanied by increased sedentary time, excessive food intake, and other unhealthy lifestyles additionally." (PMID 36313785, 2022). "Consistent with our finding, a case–control study reported that fasting blood insulin levels were higher in non-diabetic colorectal cancer patients compared with obesity-matched controls and that FI levels were associated with increased colorectal cancer risk." (PMID 35530326, 2022). "It has insulin-sensitizing effects, and its production is downregulated in obesity." (PMID 35909571, 2022). "Moreover, dietary supplementation with SEA restores pancreas lipid composition under obesity-induced insulin resistant conditions." (PMID 35158670, 2022). "Elevated fasting glucose and insulin levels are characteristic of obesity-induced IR." (PMID 36224569, 2022). "Rodent models have shown that there is an opposite sex-dependent difference that is suggested in obesity, adiposity, and insulin cohorts; these factors showed that male mice with obesity were more likely than females to have problems with metabolic homeostasis and deficits in learning and memory." (PMID 35328862, 2022). "Studies have suggested that obesity is associated with higher levels of FPG and fasting insulin." (PMID 35721805, 2022).
Obesity (continued). "Moreover, we discuss the observed plasma insulin clearance rates in the context of the observed plasma insulin concentrations to provide insight into the dose-dependent and independent effects of obesity and T2D on plasma insulin clearance." (PMID 35054781, 2022). "These ligand-activated transcription factors are involved in the regulation of numerous biological processes, including lipid synthesis and oxidation, adipocyte differentiation, glucose metabolism and insulin sensitivity, (obesity-induced) inflammation and the expression of immunoregulatory genes." (PMID 36295885, 2022). "However, a randomized clinical trial of FMT and fiber supplementation in patients with severe obesity and metabolic syndrome found significant improvements in subjects' insulin sensitivity." (PMID 36092861, 2022). "Therefore, based on these findings, increasing irisin levels and upregulating browning and beiging of WAT can be a new therapeutic strategy to treat obesity and improve insulin sensitivity to prevent GDM in overweight and obese pregnant women." (PMID 36741990, 2022). "In obesity, however, persistent O-GlcNAcylation may exacerbate both hyperlipidemia by facilitating hepatic insulin resistance to VLDL repression and amplifying de novo FFA and VLDL production." (PMID 36111295, 2022). "In addition, treatment with miRNA-690 reduces obesity-related adipose tissue inflammation and promotes repolarization of Mφs from the M1 to M2 phenotype, which also contributes to improved insulin sensitivity." (PMID 35832790, 2022). "Furthermore, autophagy has a crucial role in normal adipogenesis, and abridge of autophagy has anti-obesity and insulin-sensitizing properties." (PMID 35093121, 2022). "Cold and nutrient-activated brown adipose tissue (BAT) is capable of increasing systemic energy expenditure via the uncoupled respiration and secretion of endocrine factors, thereby protecting mice against diet-induced obesity and improving insulin response and glucose tolerance in men." (PMID 35645339, 2022). "However, there are still many open questions regarding these specific mechanisms, and more in vivo experiments with models of obesity and metabolic syndrome are needed regarding insulin homeostasis and food intake." (PMID 35458168, 2022). "We found these obvious differences in gut microbiota and microbe-derived metabolites between different groups, indicating the beneficial effects of engineered bacteria in modulating the gut-brain axis, thereby enhancing insulin action to normal levels and targeting to prevent and counteract obesity." (PMID 35293806, 2022). "Female gender, smoking status, motion sickness, the predictive use of narcotic analgesics (constituting Apfel score), history of DM (insulin dependent or insulin independent), obesity, and anesthetic regimen were considered to be potential risk factors for the occurrence of PONV." (PMID 35215349, 2022). "In addition, we have shown for the first time that CBD does not influence the thermic effect of food in males with overweight and obesity, but it does favorably modify the initial insulin and triglyceride response." (PMID 35631293, 2022). "Thus, our results are in line with previous studies, which demonstrated that IGF2BP2 deletion in mice improves glucose tolerance and insulin sensitivity and protects mice from diet-induced obesity and fatty liver." (PMID 35163144, 2022). "However, we should be aware of interstrain differences in mice models of obesity regarding thermogenesis and insulin resistance in skeletal muscles." (PMID 35323702, 2022). "Furthermore, thromboxane was elevated in genetic and dietary mice models of obesity and diabetes, while thromboxane depletion enhanced insulin sensitivity, glucose homeostasis, and CTRP9 secretion." (PMID 35370782, 2022). "Obesity is a very high risk for GDM due to glucose insensitivity and insufficient insulin response." (PMID 36558427, 2022).